TNF (tumor necrosis factor)
Diseases named in the same sentence as TNF in open-access papers (continued):
Sharing a sentence is not in itself a finding about the gene and the disease.
Crohn disease (continued). "Regular treatment of individuals with Crohn's disease includes the use of Tumor necrosis factor-a (TNF-a) inhibitors, such as Infliximab (Remicade®)." (PMID 21864366, 2011). "TNFα is most likely the most important proinflammatory cytokine in the pathogenesis of Crohn's disease as evident by the efficacy of anti-TNFα therapy in the clinics." (PMID 21915296, 2011). "Production of TNF-α in the intestinal mucosa, serum and stool is increased in patients with Crohn's disease." (PMID 21619579, 2011). "Macrophage apoptosis has also been reported in patients with Crohn's disease after anti-TNF-α treatment." (PMID 21324111, 2011). "The efficacy of adalimumab, a fully human anti-tumor necrosis factor α recombinant antibody, has dramatically improved the quality of life of patients with rheumatoid and psoriatic arthritis and Crohn's disease." (PMID 21504597, 2011). "The observations of enhanced apoptosis during anti-TNF-α treatment imply that TNF-α predominantly antagonises apoptosis in RA and Crohn's disease." (PMID 21324111, 2011). "Treatment of patients with active Crohn's disease with the TNF inhibitor infliximab has been reported to reduce gut inflammation and largely restore the gut barrier, underscoring the important role of TNF in IBD." (PMID 21853060, 2011). "For instance, Crohn's disease is associated with hyperactivation of T helper 1 (Th1) cells with abundant secretion of interferon (IFN)γ and tumor necrosis factor (TNF)." (PMID 21853060, 2011). "The local production of tumour necrosis factor alpha (TNF-α) is thought to have a key role in the initiation and propagation of Crohn's disease." (PMID 21619579, 2011). "Tumor necrosis factor alpha (TNFα) appears to be a key factor in this process, as neutralization of this critical cytokine is highly efficacious in treating both Crohn's disease and ulcerative colitis." (PMID 21806815, 2011). "Adalimumab is a relatively new anti-TNF therapy and is also licensed for the treatment of Crohn's disease." (PMID 20064220, 2010). "Etanercept bound to TNFα with a 4-fold lower affinity with respect to Infliximab, which was believed to lead to the outcome that Crohn's disease patients responded to Infliximab but Etanercept." (PMID 20140191, 2010). "Intestinal mucosal biopsies from patients with active Crohn's disease contain increased numbers of TNF-secreting cells." (PMID 21188215, 2010). "Supportive downregulation of epithelial apoptosis was found after TNF antibody treatment in patients with active Crohn's disease and in mouse models of colitis." (PMID 21188215, 2010). "Nevertheless, reducing the production or effect of TNF-α in Crohn disease patients is believed to be beneficial." (PMID 19183498, 2009). "The association between LF82 and Crohn disease is linked to up-regulation of CEACAM5 and CEACAM6 by intestinal epithelial cells, which is induced by LF82 through TNF-α secretion." (PMID 19709415, 2009). "TNF-α, in particular has been recognized as playing a central role in the pathogenesis of Crohn disease." (PMID 19183498, 2009). "The anti-TNF-α monoclonal antibody, infliximab, is already widely used to reduce gut inflammation in Crohn disease, and case reports of its effectiveness in treating refractory sprue have been published." (PMID 18425213, 2008). "Infliximab is a chimeric anti-TNF monoclonal antibody against tumor necrosis factor, an important proinflammatory cytokine in Crohn's disease." (PMID 18721465, 2008). "Treatment with infliximab, a monoclonal antibody directed against TNF-α, is used to similar effect in Crohn disease." (PMID 18425213, 2008). "Crohn's disease: Crohn's disease is characterized by increased production of IL-12 by antigen-presenting cells in intestinal tissue and interferon-γ and TNF-α by intestinal lymphocytes and macrophages." (PMID 19742267, 2008). "In the clinical setting, TNFα blockade by infliximab is demonstrated as a useful therapy for Crohn's disease." (PMID 17078892, 2006).
Crohn disease (continued). "Crohn's disease, a chronic autoimmune-mediated inflammatory bowel disease, induces sustained activation of T-cells and macrophages and elevates pro-inflammatory cytokines such as TNF-α, IL-6, and IL-17." (PMID 41523441, 2025). "Additionally, neutralizing antibodies against cytokines such as TNF-α, IL-6, and IL-12 have demonstrated efficacy in immune-mediated conditions, including Crohn’s disease." (PMID 40564127, 2025). "In fact, multiple studies have highlighted that the HS gut microbiome can mirror features of IBD: R. gnavus and C. ramosum are consistently enriched in HS and Crohn’s disease alike, contributing to a Th1-polarized cytokine milieu (elevated TNF-α, IL-12) in both conditions." (PMID 40725769, 2025). "Furthermore, in Crohn’s disease, TCRγδ+ IELs promote pathology by inducing TNF-mediated shedding of IECs, leading to villus atrophy in areas with active disease." (PMID 40307618, 2025). "Anti-TNFα antibodies in this type of pathology aim to reduce inflammation by regulating the pro-inflammatory cytokine TNFα, which is involved in the pathogenesis of chronic inflammatory bowel diseases such as Crohn’s disease." (PMID 41517255, 2025). "A similar trend was seen in patients with Crohn’s disease, where PMNs of patients with this disease released higher levels of pro-inflammatory cytokines such as TNF-α, and when stimulated with LPS the release of these pro-inflammatory cytokines increased significantly compared to PMNs of HDs." (PMID 40396174, 2025). "Supporting this, several studies have reported that treatment with TNF-α-inhibitors in Crohn’s disease patients could potentially lead to the onset of anti-NMDAR encephalitis." (PMID 41356334, 2025). "Case reports have similarly described Crohn’s disease patients developing longitudinally extensive TM while on adalimumab, supporting the possibility that TNF-α blockade may unmask or precipitate demyelinating disease in susceptible individuals." (PMID 41450349, 2025). "NbV565 was used against Crohn’s disease and was aimed at tumor necrosis factor." (PMID 41009364, 2025). "UC arises from a multifactorial interplay of genetic susceptibility, epithelial barrier defects, dysbiosis, and dysregulated mucosal immunity, which distinguishes it from Crohn’s disease (CD), where Th1/Th17 cytokine signaling and tumor necrosis factor-α (TNF-α)–driven inflammation predominates." (PMID 40869615, 2025). "Prior evidence supports these findings: cadmium exposure was shown to activate the TNF-α/NF-κB axis and upregulate inflammatory cytokines in porcine intestine, and ingestion of Ni particles worsened Crohn’s disease symptoms via interference with autophagy regulation in the colon." (PMID 41150095, 2025). "Moreover, tacrolimus has shown efficacy in related conditions, such as Crohn’s disease, where it suppresses IL-12/IL-23 p40, IL-6, and TNF-α production by activated macrophages." (PMID 40757951, 2025). "Additionally, HSPB1 exerts a role in Crohn’s disease by mediating TNF-α-stimulated myofibroblast migration and contributes to renal tubulointerstitial fibrosis by modulating E-cadherin expression through Snail downregulation." (PMID 39863585, 2025). "Furthermore, the differential impact of anti-TNF treatment on INF-γ levels in Crohn’s disease versus ulcerative colitis, and the unique increase in memory CD8+ Tc2 cells in non-responders with CD, distinguishes our work." (PMID 40244207, 2025). "Current research primarily focuses on its efficacy and safety, positioning ustekinumab as an alternative treatment option for Crohn's disease following the failure of traditional immunosuppressive therapy or tumor necrosis factor-alpha (TNF-α) antagonist treatment." (PMID 41282022, 2025). "Furthermore, we have reported that GMA induction therapy is also effective for active Crohn's disease with LOR to anti‐TNF‐α agents." (PMID 40313140, 2025).
Crohn disease (continued). "Research has indicated that Lachnospiraceae is significantly increased in the gut of patients with ulcerative colitis, and this family is closely associated with recurrent disease, adverse reactions to anti-tumor necrosis factor therapy, and post-surgical recurrence in Crohn’s disease patients." (PMID 39840995, 2025). "Furthermore, a recent study identified COTL1 among genes that were differentially expressed in Crohn’s disease patients who are resistant to the anti-tumor necrosis factor therapy." (PMID 39040043, 2024). "High serum levels of TNF-α were found in the patients of UC and Crohn’s disease." (PMID 38791116, 2024). "Concurrent pancreatic manifestations in patients with Crohn’s disease (CD) may correlate with SLR to anti-tumor necrosis factor treatment." (PMID 38472447, 2024). "When the gingival crevicular fluid Th17 cytokine protein expressions were analyzed in Crohn’s patients, similar expression profiles of IL-1β, IL-6, IL-10, IL-12p40, IL-12p70, IFN-γ, and tumor necrosis factor (TNF)-α were observed in Crohn’s disease patients and in systemically healthy controls." (PMID 38246944, 2024). "This correlation is particularly relevant given that anti-TNF agents are generally employed as advanced treatments for Crohn’s disease, aligning with our results which suggest a genetic predisposition in AS patients towards a higher necessity for advanced therapeutic interventions in CD." (PMID 39768419, 2024). "In addition, in mice that developed transmural inflammation similar to another disease, TNF‐induced Crohn's disease, the authors reported significant increases in Erysipelotrichaceae abundance." (PMID 39139979, 2024). "It was the first study that concluded that timely escalation with an anti-tumor necrosis factor therapy on the basis of clinical symptoms combined with biomarkers in patients with early Crohn’s disease results in better clinical and endoscopic outcomes than symptom-driven decisions alone." (PMID 39062093, 2024). "Finally, rs696, located in the 3′ UTR of NFKBIA gene, was associated with Guillain–Barré syndrome, Behcet disease and anti-TNF response in patients with Crohn’s disease and ulcerative colitis." (PMID 38540428, 2024). "This study assessed whether baseline triggering receptor expressed on myeloid cells [TREM-1] whole blood gene expression predicts response to anti-tumour necrosis factor [anti-TNF] therapy in patients with ulcerative colitis [UC] or Crohn’s disease [CD]." (PMID 37801628, 2024). "Current data suggest that patients with IBD who carry specific gene alleles are at high risk of low anti-TNF blood concentrations and can develop immunogenicity to these drugs, as observed in the prospective study Personalized Anti-TNF Therapy in Crohn’s Disease (PANTS)." (PMID 38612528, 2024). "Similarly, the CALM and REACT trials, which enrolled patients with established Crohn's disease in flare, found that earlier escalation to anti-TNF therapy resulted in fewer major adverse outcomes than treatment with conventional step-up strategies." (PMID 38402895, 2024). "Crude odds ratio and risk ratio of early anti-TNF therapy for sustained steroid-free mild or inactive disease without treatment intensification at one year by paediatric Crohn’s disease risk groups." (PMID 38011797, 2024). "In conclusion, the findings of the present study may greatly aid a more detailed understanding of the vast and heterogeneous anti-TNFα response in chronic immune diseases, especially Crohn’s disease." (PMID 38931955, 2024). "Both HS and Crohn’s disease have shared genetic and cytokine profiles, including the involvement of cytokines such as IL-1β and TNF-α, indicating that HS and Crohn’s disease may share therapeutic targets." (PMID 39337688, 2024). "Moreover, IL34 has been directly affiliated with Crohn’s disease by inducing TNF-α AND IL6 expression." (PMID 37740772, 2024).
Crohn disease (continued). "Whether the DNA methylation changes following smoking cessation have an impact on anti-TNF drug concentration or outcomes in patients with Crohn’s disease requires further investigation." (PMID 37551994, 2024). "Nuclear factor kappa-B activation leads to the synthesis of inflammatory molecules such as tumor necrosis factor-alpha (TNF-α) and various interleukins (IL) such as IL-1, IL-2, IL-6, IL-12, IL-16, and IL-23, which are involved in the pathogenesis of Crohn disease and ulcerative colitis (UC)." (PMID 37832114, 2023). "Herein, we report the successful continuation of VDZ as maintenance therapy without TB relapse induction in a patient with Crohn’s disease (CD) who developed anti-TNF-alpha agent-associated latent TB infection reactivation." (PMID 37443475, 2023). "For example, TNFα is a major driver of pathology during Crohn’s disease." (PMID 36645406, 2023). "Moreover, the disruption of Ruminococcus was correlated with the poor response to anti-TNFα therapy of patients with Crohn ́s disease." (PMID 37301777, 2023). "We investigated whether the response to anti-tumor necrosis factor (anti-TNF) treatment varied according to inflammatory tissue characteristics in Crohn’s disease (CD)." (PMID 37834250, 2023). "A recent study showed that LrB could reduce the severity of inflammation in Crohn’s disease colon by inhibiting the expression levels of inflammatory cytokines interleukin-1 (IL-1), IL-6 and tumor necrosis factor-alpha (TNF-α)." (PMID 37168850, 2023). "to observe the effect of anti-TNF therapy on nutritional status in patients with Crohn’s disease, investigate the correlation between the timing of anti-TNF therapy and the human body composition and examine independent body composition factors for predicting malnutrition in these patients." (PMID 36824176, 2023). "The only patient in the AIH group on TNFα antagonist therapy also had Crohn's disease." (PMID 37493768, 2023). "Interestingly, IFNγ and TNF-producing ILC1s are increased in the intestinal tissue of Crohn’s disease patients, where TNF together with IFNγ can increase permeability of the intestinal epithelial barrier leading to exacerbation of inflammation." (PMID 36969171, 2023). "TNF mAbs translated into Remicade® to treat Crohn’s disease." (PMID 36875111, 2023). "In a prospective multicenter cohort study with 1650 anti-TNF-α naïve patients with active luminal Crohn’s disease (CD), the authors have concluded that anti-TNF-α treatment failure is common and can be predicted by low drug concentrations mediated in part by immunogenicity." (PMID 37373525, 2023). "All of the patients in our study had Crohn’s disease on biological therapy with TNFα inhibitors." (PMID 37967139, 2023). "Anti-TNF agents (infliximab or adalimumab) are effective in the induction and maintenance of fistula closure and are currently recommended as the first-line medical therapy for perianal fistulising Crohn’s disease (PFCD)." (PMID 35012467, 2022). "In Crohn’s disease, nucleotide-binding oligomerization domain (NOD) 2 (NOD2), the first identified susceptibility gene, is also reduced by nicotine in HT29 cells when treated by TNF-α, implying the potential anti-inflammatory effect of nicotine on Crohn’s disease." (PMID 35251010, 2022). "Mice with a chronic overproduction of TNF-α (TNFdeltaARE mice) spontaneously develop Crohn’s disease-like inflammation in the small intestine, suggesting that TNF-α may directly induce leaky gut." (PMID 35897790, 2022). "This prospective, observational, open-label study aimed to provide access to ustekinumab prior to market authorization and assess its safety and effectiveness in patients with Crohn’s disease (CD) refractory to anti-tumor necrosis factor-α and conventional drugs in Brazil." (PMID 36362709, 2022). "Interestingly, in a case study, anti-TNF-α treatment, originally for a patient’s Crohn’s disease, also ameliorated comorbid AN in this patient." (PMID 36061277, 2022).
Crohn disease (continued). "Also, considerable human clinical data supports that therapeutic efficacy of antibody blockade of TNFα in Crohn’s disease." (PMID 35927983, 2022). "Anti–tumor necrosis factor (TNF) therapy is widely used to treat Crohn’s disease (CD)." (PMID 35529850, 2022). "Therefore, AIF-1 was able to be observed in inflamed tissues, in serum, and in cells of the immune system, and we used this capability to study its evolution in serum in patients with Crohn’s disease treated with anti-TNF." (PMID 35327530, 2022). "Indeed, the increase of CEMIP expression is observed after stimulation with TNF-α in OA chondrocytes, IL-6 in Crohn’s disease fibroblasts and IL-1β in pancreatic ductal adenocarcinoma cell line." (PMID 35474501, 2022). "Subsequently, it was further approved for other immunological diseases, including Crohn’s disease and ulcerative colitis, especially for those who have failed to respond or are intolerant to either conventional therapy or anti-TNF therapy, or have medical contraindications to such therapies." (PMID 35860015, 2022). "However, it was previously already associated with brain patterns after hypoxic-ischemic encephalopathy, fatigue in adults with HIV/AIDS, and response to anti-TNF therapy in Crohn’s disease." (PMID 35627142, 2022). "Thyroid function tests were undertaken in stored serum from biologic‐naïve adult patients with active luminal Crohn's disease immediately prior to treatment with infliximab (427 originator; 122 biosimilar) or adalimumab in the Personalised Anti‐TNF Therapy in Crohn's Disease study (PANTS)." (PMID 35768996, 2022). "Nine years of treatment for Crohn's disease with infliximab anti-TNF-α therapy was well tolerated." (PMID 36389693, 2022). "Recent studies have confirmed that combined surgery and anti-TNF therapy could improve outcomes in patients with perianal fistulising Crohn’s disease (PFCD)." (PMID 35012467, 2022). "This is the first report of not only a patient with infliximab-associated anti-NMDAR encephalitis in Crohn's disease but also of an inflammatory non-demyelinating CNS event during long-term suppression of TNF-α." (PMID 36389693, 2022). "TLR2 will provide a candidate of predictors in the Crohn’s disease anti-TNFα therapy." (PMID 35517818, 2022). "Patients with Crohn’s disease display defective innate immune responses and present with an inflammatory macrophage population that produces large amounts of pro-inflammatory cytokines such as TNF-α and IL-6." (PMID 36139127, 2022). "The PISA-II (short-term anti-TNF therapy with surgical closure vs anti-TNF therapy in the treatment of perianal fistulas in Crohn's disease) trial followed 88 patients with perianal CD comparing long-term outcomes of anti-TNF with surgical closure (n = 35) or anti-TNF monotherapy (n = 53)." (PMID 36196255, 2022). "Indeed, the group 1 signature, which characterizes two of the three Crohn’s disease CI-enriched clusters, is enriched for genes that positively regulate proinflammatory cytokines TNF and in interferon-gamma (IFNɣ)." (PMID 36313344, 2022). "The therapeutic effect of TNFα inhibitors in Crohn’s disease may be attributed to a polarization shift of macrophages from the M1 to the M2 phenotype." (PMID 36013064, 2022). "Additionally, as a paradoxical effect of anti-TNF treatment, the appearance of granulomatous pulmonary lesions was recorded in a patient with Crohn’s disease." (PMID 36421591, 2022). "Hence, this retrospective cohort study was conducted to evaluate the efficacy and safety of anti-TNF therapy in patients with stricturing Crohn’s disease." (PMID 34083575, 2021). "Indeed, enhanced levels of Erysipelotrichacea have been found in mice with TNF-driven Crohn’s disease-like transmural inflammation." (PMID 34685776, 2021). "Interestingly, other studies found that triterpene ganoderic acid C1 isolated from Ganoderma lucidum downregulated TNF-α production by macrophages and peripheral blood mononuclear cells (PBMCs) from Crohn’s disease subjects." (PMID 34305583, 2021).